GFAP (glial fibrillary acidic protein)
Diseases named in the same sentence as GFAP in open-access papers (continued):
Sharing a sentence is not in itself a finding about the gene and the disease.
Cognitive impairment (continued). "In summary, we demonstrate that plasma levels of GFAP, a measure of reactive astrocytosis in the brain, are increased a decade prior to the onset of cognitive impairment in AD." (PMID 38343809, 2024). "Mediation analyses were performed to evaluate the effects of plasma GFAP on the association between amyloid and tau PET and between tau PET and cognitive impairment and decline." (PMID 38940331, 2024). "Longitudinal studies of neuronal EV GFAP in patients with PD are warranted to further validate the correlation of GFAP with cognitive impairment in PD." (PMID 39199480, 2024). "Serum GFAP was also increased between early-stage mild cognitive impairment (MCI) individuals (n = 111) compared with those with behavioural frontotemporal dementia (P < 0.01) and controls (P < 0.001)." (PMID 39554381, 2024). "In AD-converters who are initially cognitively unimpaired, we find that higher plasma GFAP levels are observed as early as 10-years prior to the onset of cognitive impairment due to incident AD compared to those who remain cognitively unimpaired (i.e. in CU)." (PMID 38343809, 2024). "In ELS models, long-term glial activation has been related to behavioral impairments and epileptogenesis, while treatment with inflammatory inhibitors resulted in reductions of GFAP and cognitive impairments." (PMID 38593008, 2024). "The second objective is to identify and summarize all the prediction models that incorporated blood GFAP levels as a predictor of the future progression of cognitive impairment in the same two target populations." (PMID 38439065, 2024). "Plasma GFAP levels in AD-converters remain elevated 5-years prior to and coincident with the onset of cognitive impairment due to AD." (PMID 38343809, 2024). "Further, plasma pTau-181, GFAP and NfL differentiate between AD, mild cognitive impairment, and control participants, and plasma pTau-181 and GFAP increase over time in preclinical AD." (PMID 38689358, 2024). "The increase in plasma NfL and GFAP concentrations was associated with cognitive impairment and a more rapid cognitive decline in the DLB group, with a stronger association for GFAP." (PMID 38830138, 2024). "GFAP, a common marker of astroglia, was generally elevated in rodents and humans during ageing, which indicates a potential marker of cognitive impairment induced by ageing, AD, heart failure and type 2 diabetes." (PMID 37504929, 2023). "Long-term voluntary running reversed cognitive impairment, increased glial fibrillary acidic protein (GFAP) immunoreactivity, and astrocytic brain-derived neurotrophic factor (BDNF) in the hippocampus of 5xFAD mice." (PMID 37304072, 2023). "Within a population of military veterans with a history of TBI, increased GFAP and NfL concentrations have been shown to differentiate participants with cognitive impairment when measured decades after TBI." (PMID 38292036, 2023). "For the first time, increases in plasma GFAP levels were observed in our current PD cohort along with disease progression; this is consistent with previous studies on patients with mild cognitive impairment (MCI) and preclinical AD." (PMID 37932720, 2023). "Blood GFAP levels can predict not only AD development in patients with mild cognitive impairment but also cognitive decline in cognitively unimpaired subjects." (PMID 37829140, 2023). "Then, they discovered that CSF GFAP partially mediated the impacts of Aβ pathology on both hippocampal atrophy and cognitive deficits through mediation analyses." (PMID 37475029, 2023). "GFAP and ptau-181 played substantial and complementary roles in predicting brain amyloid status, with the advantage of GFAP over ptau-181 present in the cognitive impaired population." (PMID 37924152, 2023). "Overall, these results suggested that the GFAP-shHamp mice had brain iron overload accompanied by cognitive impairment, indicating the important role of astrocyte hepcidin in regulating brain iron homeostasis." (PMID 35915080, 2022).
Cognitive impairment (continued). "VX-765 treatment of aged J20 significantly reversed cognitive impairment, decreased synaptophysin immunoreactivity, and decreased dendritic spine density without increased altering pro-inflammatory cytokine levels, GFAP+-astrocytes and Iba1+-microglia numbers." (PMID 36220815, 2022). "Lin28a siRNA treatment alleviated cognitive impairment and overexpression of GFAP and Iba-1 in the brain." (PMID 35453602, 2022). "Structural equation modeling revealed that CSF GFAP and YKL-40 mediate the effects of Aβ and tau, respectively, on hippocampal atrophy, which was further associated with cognitive impairment." (PMID 35948658, 2022). "Plasma-EVs expressing CD14, CD16, CD192, C195, and GFAP were significantly higher in HIV-infected individuals with cognitive impairment compared to individuals with normal cognition." (PMID 36601110, 2022). "Deamidation biomarkers performed superiorly (accuracy up to 92%) compared with blood biomarkers Aß42/Aß40, NfL, GFAP and p-tau181 in separating mild cognitive impairment from healthy controls." (PMID 36575499, 2022). "Here, VX-765 reversed cognitive deficits without altering increased pro-inflammatory Iba1+-microglia, Il-1β, TNF-α, and GFAP+-astrocytes, thereby seemingly excluding inflammation as a driver of cognitive impairment." (PMID 36220815, 2022). "In APOE ε4 non-carriers, most of these protein levels were similar to controls, except for inflammation markers SPP1, FABP3 (also in the replication cohort), and GFAP that were higher in more severe stages of cognitive impairment." (PMID 32460813, 2020). "Pilo induced cognitive deficits, cell damage, increased GFAP, Iba-1, and GAT1 expression in the hippocampus." (PMID 32545390, 2020). "Collectively, out of all markers investigated, GFAP correlated best with both Aβ and tau pathology as well as cognitive deficits, suggesting that astrocytes track both disease progression and pathology." (PMID 32514860, 2020). "β-Asarone improved cognitive impairment, alleviated Aβ deposition and hippocampal damage, and inhibited GFAP, AQP4, IL-1β, and TNF-α expression." (PMID 29599803, 2017). "The administration of minocycline in 8-month-old 3xTg-AD mice was also shown to prevent cognitive deficits and to decrease insoluble Aβ and soluble fibrils via the reduction of inflammatory agents such as GFAP, TNF-α and IL-6." (PMID 22339795, 2012). "Notably, some studies have found that plasma GFAP shows stronger associations with the Aβ burden, cognitive decline, and conversion from mild cognitive impairment (MCI) to AD than CSF GFAP." (PMID 40943059, 2025). "Moreover, GFAP expression is elevated in mice after the successful induction of cognitive deficits with STZ-icv." (PMID 40450637, 2025). "In our study, we found resistance to cognitive deficits and cerebellar oxidative stress in females, suggesting that cerebellar GFAP content may be a sign of protection in contrast to reactivity." (PMID 40429951, 2025). "However, our findings indicated that plasma p-tau181 and GFAP were more accurate than p-tau217 in distinguishing cognitive impairment in the very elderly population." (PMID 41180536, 2025). "GFAP is key biomarker of neural damage and cognitive impairment." (PMID 40512435, 2025). "Increasing neurofilament light chain and glial fibrillary acidic protein levels, but not change in the amyloid-β42/40 ratio or phosphorylated tau 181, were associated with worsening cognitive function and incident cognitive impairment." (PMID 39913137, 2025). "In recent years, GFAP has gained attention as a promising biomarker for cognition impairment in PD." (PMID 39199480, 2024). "Taken together, while conventional amyloid and tau pathology are valuable as AD diagnosis biomarkers, our results suggest that plasma NFL and GFAP may be useful as prognosis biomarkers for cognitive impairment." (PMID 38994939, 2024).
Cognitive impairment (continued). "The correlation of GFAP with brain atrophy also raises a question of whether GFAP could help to predict future cognitive impairment." (PMID 39238198, 2024). "GFAP is a promising biomarker for predicting cognitive impairment in individuals with early AD." (PMID 38439065, 2024). "Our results also suggest that changes in plasma GFAP levels may begin even earlier than 10 years prior to the onset of cognitive impairment in patients who eventually develop AD." (PMID 38343809, 2024). "Reactive astrocytes, as measured by cerebrospinal fluid (CSF) levels of glial fibrillary acidic protein (GFAP), have been shown to mediate the effect of Aβ on tau and drive downstream neurodegeneration and cognitive impairment in patients with AD and preclinical AD." (PMID 38502413, 2024). "Rb1 could relieve cognitive deficits by decreasing expressions of IL-1β, Aβ, and glial fibrillary acidic protein (GFAP) and alter the amyloidogenic process of APP into the nonamyloidogenic process in AD rats by exerting anti-inflammatory." (PMID 38957183, 2024). "Longitudinal studies that track the changes in astrocyte mitochondrial activity and GFAP intensity in response to sera collected over time could provide insights into the progression of depressive and cognitive disorders." (PMID 39175522, 2024). "In summary, plasma GFAP, being strictly associated with amyloid co-pathology in ALS, could serve as a biomarker of cognitive impairment in ALS and aid in identifying patients with cognitive features atypical for ALS-FTD dementia." (PMID 37762278, 2023). "In sum, GFAP presents as a potential indicator of cognitive impairment in PD." (PMID 37475029, 2023). "To evaluate whether cognitive impairment detected in rats inoculated with FAβ1–42 peptide solution (1 μg/μL) was correlated with astrogliosis, we performed GFAP fluorescence labeling of brain tissues of rats harvested at 14 days post-infusion." (PMID 36899831, 2023). "Interestingly, GFAP has also been identified as a blood biomarker in AD patients and correlates with cognitive impairment." (PMID 36877047, 2023). "Preliminary findings revealed that PD patients who had greater baseline CSF GFAP levels experienced more rapid cognitive deterioration during follow-up, indicating that CSF GFAP may be a predictor of cognitive impairment progression." (PMID 37475029, 2023). "GFAP and chitinase-like 1 are differentially related to AD but both may mediate brain atrophy and cognitive impairment." (PMID 36499477, 2022). "A separate study conducted in 114 older adults with unimpaired cognition, mild cognitive impairment, or AD reported that plasma GFAP levels explained 25% of the variance in memory, as well 10%–15% of the variance in visuospatial, language/semantic knowledge, and executive function domains." (PMID 36056631, 2022). "However, we found significant elevations in levels of EVs expressing monocyte-associated markers in HIV+ persons with cognitive impairment including CD14+EVs, CD16+EVs, CD192+EVs, CD195+EVs, as well as EVs expressing glial fibrillary acidic protein (GFAP)." (PMID 36601110, 2022). "Moreover, GFAP emerged as the most robust indicator of disease progression, tau/Aβ pathology, and cognitive impairment." (PMID 32514860, 2020). "We also aimed to examine the association between WMH burden and both GM atrophy and cognitive deficits in FTD, as well as the association with fluid markers of axonal damage (neurofilament light chain, NfL) and astrocytosis (glial fibrillary acidic protein, GFAP)." (PMID 31835286, 2019). "A single systemic treatment with the TNF-α synthesis inhibitor 3,6′-dithiothalidomide 1 h post injury prevented the mTBI-induced TNF-α elevation and fully ameliorated the neuronal loss (NeuN), elevations in astrocyte number (GFAP) and BID, and cognitive impairments." (PMID 25879458, 2015). "This is similar to the early development of cognitive deficits in GFAP-apoE4." (PMID 22028984, 2011).
Cognitive impairment (continued). "Interestingly, cognitive impairment is evident at an earlier age in female compared to male GFAP-apoE4 mice." (PMID 22028984, 2011). "While the antidepressant‐like effects of vitamin C suggest a potential GFAP‐independent mechanism, its inability to ameliorate cognitive deficits raises the possibility that astrocytic dysfunction, particularly the loss of GFAP expression, may play a causal role in stress‐induced memory impairment." (PMID 40855793, 2026). "Therefore, serum GFAP may be a better indicator of cognitive impairment than NfL when MCI is diagnosed by physicians, especially when the type of MCI is not distinguished." (PMID 38352136, 2024). "The final marker of brain injury was GFAP, which is specific to astrocytes; an increase in its level in the patient’s blood indicates a disruption in the integrity of the blood–brain barrier (BBB) and is also associated with postoperative cognitive impairments." (PMID 39458000, 2024). "These associations seem to be driven by the results in the group of participants with cognitive impairment suggesting that plasma GFAP may be useful as a marker for the prediction of future or more severe NPS in particular in patients presenting with cognitive impairment." (PMID 39054505, 2024). "Moreover, plasma GFAP has been associated with brain amyloid pathology and cognitive impairment in humans, but it is not widely studied, and its dietary response has not been investigated." (PMID 39619979, 2024). "However, HCRTR1 antagonists and GFAP‐HCRTR1‐KD both reversed cognitive impairment in CUMS mice." (PMID 39119889, 2024). "Given that increased plasma GFAP may be an early marker of some amyloid-β and Tau-related pathologies, further studies are warranted to investigate its relationship to biotypes of cognitive impairment in PWH." (PMID 38257772, 2023). "Therefore, GFAP could be a potential biomarker for diagnosis, prognosis prediction, and progression evaluation of AD, especially in relation to brain damage and cognitive impairment." (PMID 37174709, 2023). "The central aim of our investigation was to assess cognitive impairment and to analyze the relationship between specific biomarkers - BDNF, BACE1, VEGF, GFAP and IL-1β and cognitive dysfunction in adults PWE." (PMID 40291844, 2025). "The correlation between glial fibrillary acidic protein (GFAP) and cognitive impairment in acute ischemic stroke patients remains uncertain." (PMID 40421099, 2025). "Further, we investigated the relationship between cognitive impairment and the possible roles of serum BDNF, BACE1, VEGF, and GFAP as potential biomarkers for cognitive impairment in people with epilepsy." (PMID 40291844, 2025). "Here, we investigated plasma Glial Fibrillary Acidic Protein (GFAP), Neurofilament Light Chain (NfL) and Phosphorylated-tau-181 (pTau 181) in AD and in its early stages: Subjective cognitive decline (SCD) and Mild cognitive impairment (MCI)." (PMID 38654932, 2024). "Plasma GFAP shows the highest accuracy among the most common plasma biomarkers in identifying AD co-pathology in ALS and is related to measures of cognitive impairment in ALS patients." (PMID 37762278, 2023). "Increased CSF-EVs expressing GFAP and CD200 were found in the cognitive impairment group compared to the normal cognition group." (PMID 36601110, 2022). "One study found that GFAP levels normalized in all COVID-19 patients despite disease severity and the persistence of reported cognitive symptoms suggesting that the symptoms of COVID-19-associated cognitive impairment linger without the presence of active CNS injury." (PMID 36268187, 2022). "NSE, S100β, and GFAP are considered to negatively correlate with TBI severity and prognosis, and to represent cognitive deficits." (PMID 36034283, 2022).
Cognitive impairment (continued). "To determine whether cognitive deficits are correlated with Aβ-related brain pathology, we immunostained coronal brain sections from AppNL-G-F/NL-G-F, AppNL/NL and WT mice with the anti-Aβ antibody 82E1, anti-Iba1 antibody as a microglial marker, and anti-GFAP antibody as an astrocytic marker." (PMID 30894120, 2019). "Serum levels of BDNF, BACE1, VEGF, GFAP, and IL-1β were evaluated through ELISA in patients with and without cognitive impairments." (PMID 40291844, 2025). "Glial fibrillary acidic protein (GFAP) as a marker of glial activation was first reported to increase and to correlate with cognitive impairment in AD patients in 2019 and has since been validated as a valuable biomarker for AD, although with significant variability." (PMID 40806401, 2025). "Plasma GFAP levels are elevated in β-amyloid–positive individuals and in those with mild cognitive impairment (MCI), regardless of cognitive status, and correlate with higher β-amyloid PET signal, even after controlling for tau." (PMID 41465278, 2025). "Specifically, 2 d group showed an increase in Iba-1 and GFAP positive cells in some regions, yet they did not exhibit any cognitive impairment." (PMID 41254121, 2025). "The strong GFAP reduction in PFZ mice (from 51.33 to 11.53 pg/mg) correlated with their improved performance in all behavioral assays, emphasizing the link between neuroinflammation and cognitive impairment." (PMID 41164371, 2025). "Our results demonstrated that T3 treatment reversed cognitive impairment and increased Akt and GSK3 phosphorylation in the treated group, while also reducing microglial activation (Iba-1) and GFAP expression (reactive astrocytes), along with TNF-α, IL-6, and IL-1β levels in the hippocampus." (PMID 39513900, 2024). "Various studies reported pathological astrogliosis, both in AD patients and in transgenic animals, characterized by an increase in the glial fibrillary acidic protein (GFAP) and a distinct cellular hypertrophy, which somehow correlates with the severity of cognitive impairment in AD patients." (PMID 37833898, 2023). "The rate of change in GFAP concentrations was significantly higher among individuals who developed clinical AD than those with no cognitive impairment." (PMID 37174709, 2023). "In conclusion, we demonstrate that the levels of plasma GFAP are elevated in PD patients with cognitive impairment, but not in PD patients with normal cognition." (PMID 36759508, 2023). "Our analysis revealed that the GFAP level in the blood was higher in the Aβ-positive group than in the negative groups, and in individuals with AD or mild cognitive impairment (MCI) compared to the healthy controls." (PMID 37174709, 2023). "COVID-19 patients demonstrated higher levels of NfL and GFAP in comparison to non-COVID controls with mild cognitive impairment (MCI) or AD." (PMID 38187359, 2023). "Among the HIV-infected group, GFAP-infected exosomes are significantly higher in those with normal cognitive infection when compared with those with cognitive impairment (p = 0.029)." (PMID 35720083, 2022). "More importantly, hyperforin treatment significantly reduced Aβ deposition, GFAP expression, levels of IFN-γ, IL-1β, IL-6, and TNFα, and improved performance in behavioral tests, suggesting reversal of cognitive deficits." (PMID 35077394, 2022). "Subjects with HIV-associated neurocognitive disorders had higher abundance of CSF extracellular vesicles and proteins related to synapses, glial cells (incl., GFAP, S100B), inflammation, and stress responses vs. patients without cognitive impairment." (PMID 33115334, 2021).